SERPINB2 (serpin family B member 2)
Diseases named in the same sentence as SERPINB2 in open-access papers (continued):
Sharing a sentence is not in itself a finding about the gene and the disease.
lung fibrosis (2 papers, 2023 to 2025). "In the peripheral blood of SSc‐ILD patients, upregulated genes including S100A8, S100A12, ADAMTS2, IFNG, and SERPINB2 were identified, which have been linked to the progression of lung fibrosis." (PMID 40165483, 2025). "Serpinb2 is an inhibitor of extracellular uPA and might be related to lung fibrosis development." (PMID 36732560, 2023).
papilloma (2 papers, 2015 to 2019). A benign epithelial neoplasm that projects above the surrounding epithelial surface and consists of villous or arborescent outgrowths of fibrovascular stroma. "It has been shown that overexpression of SERPINB2 in keratinocytes enhances papilloma formation in transgenic mice and knockout of SERPINB2 abrogates papilloma formation in mice." (PMID 26338969, 2015).
pneumococcal infection (2 papers, 2022 to 2025). Infections with bacteria of the species streptococcus pneumoniae. "Serpinb2−/− mice exhibited increased C5a levels, but decreased IL-10 levels in the brain during pneumococcal infection." (PMID 36309755, 2022).
alcoholic liver cirrhosis (1 paper, 2023). A disorder of the liver characterized by the presence of fibrotic scar tissue instead of healthy liver tissue. "SERPINB2 mono was more enriched in the PBMCs than in the liver of patients with alcoholic liver cirrhosis." (PMID 36845083, 2023).
Anxiety (1 paper, 2024). Intense feelings of nervousness, tension, or panic often arise in response to interpersonal stresses. "We found that manipulation of Serpinb2+ neuronal activity did not affect locomotion in an open field test, conditioned place preference (CPP), cocaine CPP test, anhedonia in sucrose preference test, social interaction or anxiety in the elevated plus maze test." (PMID 39147933, 2024).
bacterial meningitis (1 paper, 2022). Inflammation of the membranes surrounding the brain and spinal cord due to a bacterial infection. "We analyzed the function of SERPINB2 (coding for PAI-2) in patients with bacterial meningitis, in a well-established pneumococcal meningitis mouse model, using Serpinb2 knockout mice, and in vitro in wt and PAI-2-deficient bone marrow-derived macrophages (BMDMs)." (PMID 36309755, 2022).
carcinosarcoma (1 paper, 2017). A malignant tumor composed of a mixture of carcinomatous and sarcomatous elements. "In the present study, SerpinB2 expression level was investigated in carcinosarcoma-derived Hs578T cell (MSL subtype), ductal carcinoma-derived HCC-38 cell (BL1 subtype) and invasive ductal carcinoma-derived MDA-MB-231 cell (MSL subtype)." (PMID 28427146, 2017).
chronic kidney disease (1 paper, 2022). Impairment of the renal function secondary to chronic kidney damage persisting for three or more months. "The SERPINB2 gene encoding the protein plasminogen activator inhibitor 2 is associated with the delayed development of DN and chronic kidney disease." (PMID 36304455, 2022).
esophageal cancer (1 paper, 2022). A primary or metastatic malignant neoplasm involving the esophagus. "To investigate the function of SERPINB2 in esophageal cancer cells, we performed knockdown experiments using antisense oligonucleotides (ASO)." (PMID 36497110, 2022). "Here, we identify 2444 EGCG-regulated genes in esophageal cancer cells, including SERPINB2." (PMID 36497110, 2022). "Our study demonstrates that SERPINB2 is a new tumor-suppressor gene involved in cell movement and apoptosis and could be a therapeutic target for esophageal cancer." (PMID 36497110, 2022). "In this study, we demonstrated that SERPINB2 was a tumor suppressor which inhibited metastasis and induced apoptosis, suggesting that it could be a novel therapeutic target for treating esophageal cancer." (PMID 36497110, 2022). "However, the function of SERPINB2 has not been characterized in esophageal cancer." (PMID 36497110, 2022).
fracture (1 paper, 2021). "First, in our study, SERPINB2 siRNA combined with atelocollagen was injected locally into the fracture site, and SERPINB2 silencing successfully accelerated bone healing in a murine tibial fracture model." (PMID 34620242, 2021).
gestational trophoblastic disease (1 paper, 2012). "SERPINB2 plays a role in the placenta during early pregnancy at 8–10 weeks, is very highly expressed in this tissue, is purported to be involved in gestational trophoblastic disease and in malignant neoplastic progression." (PMID 22253721, 2012).
glaucoma (1 paper, 2022). Increased pressure in the eyeball due to obstruction of the outflow of aqueous humor. "A detailed investigation in this line may give insight into the involvement of SERPINB2 and other members of this family in the pathogenesis of GC-induced glaucoma." (PMID 35585182, 2022).
Granuloma (1 paper, 2021). A compact, organized collection of mature mononuclear phagocytes, which may be but is not necessarily accompanied by accessory features such as necrosis. "A deficiency of SERPINB2 in the livers of murine models of the helminth Schistosoma japonicum infection results in a reduction in the deposition of collagen within the egg-induced granuloma." (PMID 34648138, 2021).
histiocytic lymphoma (1 paper, 2014). "Phorbol ester treatment of the human histiocytic lymphoma cell line, U937, represents a well-recognized system for studying SerpinB2 secretion." (PMID 24644264, 2014).
HIV-1 infection (1 paper, 2013). The type species of lentivirus and the etiologic agent of acquired immunodeficiency syndrome (AIDS). "These analyses of published microarray studies thus provide evidence that during HIV-1 infections in humans, SerpinB2 is induced in monocytes and that SerpinB2 expression correlates with modulation of Th1/Th2 responses." (PMID 23460840, 2013). "The human microarray analysis suggests that during HIV-1 infection in humans, higher SerpinB2 mRNA levels correlate with suppression of Th1 (T-bet) responses; a Th1 modulation similar to that seen in SerpinB2−/− mice after vaccination with a Th1-promoting vaccine." (PMID 23460840, 2013). "SerpinB2 has been shown to modulate Th1/Th2 responses in the EcoHIV mouse model and two other mouse models, with correlative evidence suggesting this may also be the case in human HIV-1 infections in vivo and several other human inflammatory diseases." (PMID 23460840, 2013). "Taken together with analysis of published microarray data from human HIV-1 infections, the data presented herein supports the view that SerpinB2 is induced during SIV and HIV infections, and that SerpinB2 modulates anti-lentiviral Th1/Th2 responses." (PMID 23460840, 2013).
kidney injury (1 paper, 2025). Trauma to the kidney. "In particular, Serpinb2 has been reported to link to the enhancement of CCL2 expression and the regulation of macrophage function in the context of kidney injury." (PMID 40485847, 2025).
liver fibrosis (1 paper, 2025). "Notably, although it currently has no characteristic role in hepatic stellate cell activation or fibrosis, this suggests that SERPINB2 may be a new marker for the identification of liver fibrosis." (PMID 39936105, 2025).
malaria (1 paper, 2025). Malaria is a serious and sometimes fatal disease caused by a parasite that commonly infects a certain type of mosquito which feeds on humans. "The malaria-induced expression of Serpinb2 showed a significantly faster increase in transcript levels between day 4 p.i. and day 8 p.i. in the liver of unvaccinated mice than in vaccinated mice, resulting in lower transcript levels at peak parasitaemia in vaccinated mice." (PMID 40243929, 2025).
myeloma (1 paper, 2015). "Intriguingly, a common SerpinB2 polymorphism is associated with susceptibility to dose limiting peripheral neuropathy in myeloma patients undergoing therapy with the proteasome inhibitor Bortezomib." (PMID 26083412, 2015).
neuroblastoma (1 paper, 2020). Neuroblastoma (NB) is the most common solid, extracranial childhood tumor. "SERPINB2 is another upregulated gene in neuroblastoma cells following BI 2536 treatment." (PMID 32231733, 2020).
oral cancer (1 paper, 2021). "Moreover, four genes (SERPINB2, GFOD1, TGFA, MXD1) were downregulated in these samples suggesting an inhibitory role in oral cancer cell invasion and metastasis." (PMID 34116687, 2021).
parasitic infections (1 paper, 2022). "Moreover, studies have also shown that SERPINB2 regulates TH1/TH2 adaptive immune response in inflammatory, viral, and parasitic infections." (PMID 34992733, 2022).
prostate tumor (1 paper, 2020). "SERPINB2 was upregulated in treated PC1 cells as in primary canine prostate tumor, but downregulated in treated PC2 cells." (PMID 33324695, 2020). "Therefore, we found FABP3 and SERPINB2 as common genes in our treated samples and primary prostate tumor in dogs, with increase of FABP3 in all our comparative samples, but interestingly SERPINB2 was downregulated only in PC2, which was resistant to TP." (PMID 33324695, 2020).
skin cancer (1 paper, 2022). "Thus we conclude that in contrast to results obtained in the HRASQ61L-driven murine skin cancer model, SERPINB2 is not a mediator of the effects of DUSP5 loss in the pancreas." (PMID 35418690, 2022).
thyroid carcinoma (1 paper, 2018). "We focused our attention on: CAV1, a 22 kDa protein considered as an indicator of thyroid carcinoma progression and serpinB2 (PAI2), a Plasminogen Activator Inhibitor that can reportedly act as a suppressor of tumor growth and metastasis formation." (PMID 29487711, 2018).
tumor (95 papers, 1991 to 2026). "In line with these discoveries, we have found that high levels of SERPINB2 are associated with a low tumor stage and an improved distant metastasis-free survival (DMFS) in ER-negative breast tumors." (PMID 38741146, 2024). "In ER-negative breast tumors, we found that high SERPINB2 levels are associated with a low tumor stage and an improved distant metastasis-free survival (DMFS)." (PMID 38741146, 2024). "Generally, SERPINB2 expression in tumor tissues is negatively associated with cancer growth and metastasis." (PMID 37884951, 2023). "This implies that SerpinB2 is associated with tumorigenesis, invasion, and metastasis in the complex tumor system." (PMID 35768767, 2022). "Loss of expression of SerpinB2 was, however, shown to be associated with the activation of tumor growth and metastasis in several cancer types, including BC32–34." (PMID 31308359, 2019). "Overexpression of plasminogen activation system members, including uPA, SerpinE1 and SerpinB2, is associated with malignancy, tumor progression, and metastasis." (PMID 28427146, 2017). "In contrast to these studies, our IHC results showed that high levels of SerpinB2 in cancer cells within the primary tumor tissue were associated with reduced OS for all BC patients." (PMID 28427146, 2017). "Many studies have linked SerpinB2 to macrophage survival as well as the tumor-associated M2 phenotype in lung metastasis." (PMID 28427146, 2017). "While SerpinB2 has been studied with respect to extracellular matrix remodeling, tumor growth, and metastasis in diverse cancers, its association with patient prognosis is unclear." (PMID 28427146, 2017). "The clear suggestion is that SerpinB2 associated with tumor-derived MPs inhibits MP-associated uPA, thereby inhibiting tumor cell migration, invasion, and metastasis." (PMID 24644264, 2014). "SerpinB2 deficiency is associated with a dysregulation of the Th1- and Th2-promoting cytokine release, which has traditionally been viewed as inhibiting and favoring tumor growth." (PMID 38956496, 2024). "SerpinB2 has also been implicated in the tumor suppression and promotion functions of TAMs." (PMID 38956496, 2024). "Similarly, aberrant activation of SERPINB2 has been reported to be significantly associated with tumor progression (metastasis) and poor prognosis in various cancer types, such as endometrial, colorectal, ovarian, and bladder cancers." (PMID 35932085, 2022). "Importantly, SERPINB2 expression has also been associated with tumor initiation, progression and metastasis in various cancers, such as bladder, colorectal, endometrial and ovarian cancers." (PMID 30965654, 2019). "Thus, low SerpinB2 could potentially be associated with increased tumor progress by angiogenesis and tumor invasion." (PMID 29207598, 2017). "Proteomic profiling further revealed its impact on multiple oncogenic and tumor-suppressive proteins, with notable upregulation of SERPINB2, KIT, and NOTCH1, alongside downregulation of COX2, DNMT1, MAPK1, AKT1, MKI67, EP300, and SMC1A." (PMID 41321870, 2025). "Specifically, in TNBC cells we find that ALDH1A3 can transcriptionally regulate PLAT, PLAU, and SERPINB2; however, considering both the cell line and patient tumour data, the strongest overall evidence was between ALDH1A3 and PLAT/tPA." (PMID 37753740, 2024). "The following observations support our finding: an increase in NOS2-positive M1 macrophages and a decrease in CD206-positive M2 macrophages in the tumor tissues of PyMTSB2−/− mice and the SerpinB2 knockdown RAW264.7 cells." (PMID 38956496, 2024). "The inhibitory effects of Id1 deletion in TAMs on both tumor growth and liver metastasis were completely abrogated when Ccl4 and Serpinb2 were depleted simultaneously." (PMID 37996458, 2023). "Conversely, genes involved in cell death (Aifm3, FC = –1.9, P = 0.04) or tumor suppression (SerpinB2, FC = –35.0, P = 7 × 10–4; Arhgap15, FC = –3.6, P = 0.03; Frk, FC = –1.7, P = 0.01) were downregulated." (PMID 36892943, 2023).
tumor (continued). "Herein we identified SERPINB2 as an EGCG-regulated tumor-suppressor gene that was mediated by NF-κB and confirmed the role of SERPINB2 in cell migration and apoptosis." (PMID 36497110, 2022). "In vitro, SERPINB2-deficient cancer cells are associated with increased tumor growth, aberrant ECM, and invasive properties, while SERPINB2 overexpression inhibits tumor proliferation and migration." (PMID 36241983, 2022). "SerpinB2 is highly expressed in immune and tumor cells and is involved in multiple biological functions, including cell survival and remodeling for disease progression." (PMID 35768767, 2022). "More importantly, SERPINB2 was directly related to tumor promotion and poor prognosis in various cancers such as bladder, colorectal, endometrial, and ovarian cancers." (PMID 36497110, 2022). "More strikingly, we also found that SERPINB2 expression was substantially increased in multiple cancer types compared to non-tumor tissues, suggesting that SERPINB2 is a reliable marker for predicting tumorigenicity." (PMID 30965654, 2019). "Despite shared serpin function, high tumor levels of SERPINE1 promote tumor progression, whereas high levels of SERPINB2 appear to decrease tumor growth and metastasis." (PMID 29487711, 2018). "Lung metastatic tumor tissue immunohistochemistry (IHC) analyses revealed that miR-200c/141 overexpression upregulated SerpinB2 in cancer cells, but downregulated SerpinE1." (PMID 28427146, 2017). "Lung metastases were greater in number and mass in MDA-MB-231miR-200c/141 tumors compared to controls, and SerpinB2 overexpression was observed in MDA-MB-231miR-200c/141 tumor lung metastases." (PMID 28427146, 2017). "In patient tumor samples, higher SerpinB2 levels were detected in TNBC as compared to other BC subtypes, and were associated with LN metastasis and reduced survival." (PMID 28427146, 2017). "This difference in prognostic impact has not been presented before, and potentially reflects differences in how SerpinB2 affects tumor biology in AC and SCC at the early stages." (PMID 29207598, 2017). "SerpinB2 is overexpressed in tumor tissues relative to corresponding normal tissues, and has been clinically associated with poor prognosis in primary breast and other solid cancers." (PMID 28427146, 2017). "In xenografts and TN patient tumor samples, high SerpinB2 expression was also observed in macrophages and fibroblasts in adjacent stromal tissue." (PMID 28427146, 2017). "The biological function of SerpinB2 is known to some extent, but its complete role in human cancer progression, and in different tumor types, is controversial." (PMID 29207598, 2017). "To further validate our in vitro findings of the effects of YD on the expression of key markers including SerpinB2, uPA, E-cadherin and N-cadherin, we evaluated the effects of YD in tumor tissues." (PMID 27558531, 2016). "Although no tumor was found in animals (n = 5) injected with cells transfected with vector, all animals injected with cells expressing SLC30A1 (n = 5) or SERPINB2 (n = 4) developed tumor at the xenograft site within 4 weeks after injection." (PMID 26338969, 2015). "SerpinB2-expressing B16 cells also showed reduced migration and increased length of invadopodia-like structures, supporting the classical view that that tumor-derived SerpinB2 is inhibiting extracellular urokinase." (PMID 24644264, 2014). "Herein, we use SerpinB2−/− mice to explore the role of host cell SerpinB2 expression, and use lentiviral transduction of syngeneic tumor cell lines to explore the role of murine SerpinB2 in immunologically intact mice." (PMID 24644264, 2014).